IL6 (interleukin 6)
Diseases named in the same sentence as IL6 in open-access papers (continued):
Sharing a sentence is not in itself a finding about the gene and the disease.
infection (continued). "Infection of NOD1/2 KO mice with wildtype of B. abortus or infection of wildtype mice with the VceC null mutant yields decreased IL6 production, milder pathology and increased survival of mice." (PMID 34201509, 2021). "p75(NTR) was upregulated upon infection and affected innate immune cell behavior to producing the cytokines: IL-10, IL-6, and IL-1α." (PMID 34124260, 2021). "Our studies have shown that differences in the levels of IL-8 and IL-6 detected by flow cytometry are related to infection time, strain type, and cell line." (PMID 34835359, 2021). "Under normal conditions, the concentration of IL-6 is relatively low, and it dramatically increases when an event that promotes immune response occurs, e.g., injury or infection." (PMID 33435569, 2021). "The cytokine response to SARS-CoV-2 infection was found to increase by 3°days post infection, and eventually decline to the baseline level by 14°days post infection, with the exception of IL-6 and IL-1Ra with sustained upregulation." (PMID 33912590, 2021). "The optimal infection period was also investigated, with assessment of Pa-induced IL-6 and CXCL8 at 2, 4, 8, 12 and 24 hours post infection." (PMID 33524056, 2021). "CRP is an acute phase reactive protein that is induced by interleukin-6 under stress states, including infection and synthesis by the liver." (PMID 34290800, 2021). "(M–P) Gene expression analysis of Tnf (M), Casp1 (N), Il1b (O), and Il6 (P) in hypothalamus of young and old mice 8 days post-infection." (PMID 34151773, 2021). "Twelve hours after infection, the levels of circulating inflammatory cytokines (IL-1β, IL-6, IL-18, and TNF-α) were still hardly detectable in most of the animals." (PMID 34236052, 2021). "This study demonstrated that CdtB promoted the progression of inflammation within 24 weeks in B6.129P2-IL10tm1Cgn/J mice infected with H. hepaticus, and up-regulated the transcription of Il-6 and Tnf-α in the proximal colon during infection." (PMID 33777833, 2021). "During infection and inflammation, IL-6 and other cytokines aid to increase the synthesis of hepcidin leading to sequestration of iron in the macrophages." (PMID 33994996, 2021). "Prior studies have found that expression of key inflammatory cytokines known to be increased during infection with SARS-CoV-1 (IL-1β) and SARS-CoV-2 (TNFα and IL-6) is increased during infection with MHV-A59 as well." (PMID 34479991, 2021). "Mincle KO mice also displayed a subtle elevation in serum IL-6 levels 1-week post infection with C. tropicalis likely due to the increased fungal burden in these mice." (PMID 33717025, 2021). "Here, we showed that STING is not only required for expression of IFN-β in T. cruzi-infected RAW264.7 macrophages but also promotes IL-6 and IL-12 expression, which are involved in host resistance to infection." (PMID 35095849, 2021). "At 6, 24, 48, and 72 h post infection, blood samples were collected, and the serum levels of 10 cytokines (GM-CSF, IL-1β, IL-6, IL-10, TGF-β1, IFNγ, IL-4, IL-8, IL-12p40, and TNF-α) were assessed." (PMID 33665221, 2021). "In the trachea, the IL-6 mRNA expression in group IV was significantly lower (p < 0.05) compared with IL-6 mRNA expression in group I at day 3–7 post-infection." (PMID 34988139, 2021). "In mice, production of an active CDT by H. hep promotes the hepatic expression of TNFα, IFN-γ, Cox2, Interleukin-6 (IL-6) and the NF-κB subunits p50 and p65 4 months post-infection." (PMID 34308492, 2021). "Cytokines, such as TNF-α and IL-6, are produced by the immune system following infection and are necessary for tissue repair." (PMID 34071911, 2021). "The inflammation response is a hallmark of host defense upon pathogenic infection in fish; as expected, we observed a significant increase in the expression of pro-inflammatory cytokines tnfa, il1b, il6, and cox2 upon infection with IPNv." (PMID 34768822, 2021).
infection (continued). "Interleukin-6 (IL-6) is a soluble mediator which is produced immediately and transiently in response to tissue injury and infection." (PMID 33912039, 2021). "Consistent with this idea, BMDMs and MEFs from Rnf122−/− mice produced increased levels of IFNα and IFNβ, TNFα and IL6 in response to infection with VSV and SeV." (PMID 33808506, 2021). "Among cytokines, chemokines and growth factors reported, IL-6 is the most common cytokine which was upregulated during infections with many viruses including SARS-CoV-2, SARS-CoV, HIV, EBOV, IAV, RSV, CSFV and HNoV." (PMID 34578457, 2021). "Our results demonstrate that infected epithelial cells at the earliest stages can produce IL-6, which potentially contributes to the cascade of inflammatory disease that occurs later during infection." (PMID 33507952, 2021). "Infection induces the production of proinflammatory cytokines and chemokines such as interleukin-8 (IL-8) and IL-6." (PMID 34073283, 2021). "Fth1−/− mice had lower levels of circulating tumor necrosis factor (TNF)-alpha, interferon-gamma (IFN-gamma) and interleukin (IL)-6 than Fth1+/+ mice, 60 days after infection." (PMID 35008695, 2021). "This infection and/or inflammation of the intra-uterine results in an increase in the level of pro-inflammatory cytokines, such as interleukin-6 (IL-6) in the plasma of the fetus, which defines the syndrome of fetal inflammatory response." (PMID 34079778, 2021). "We found that cells infected with SARS-CoV-2 released higher levels of cytokines when compared with MOCK, with the exception of IL-8 at 24 and IL-6 at 72 h post-infection." (PMID 34707939, 2021). "We found that Rufomycin 4–7 effectively decreased the generation of pro-inflammatory cytokines Il1b and Il6 in macrophages as well as the intracellular survival of type strain and two clinical isolates of Mabs-R during infection." (PMID 34447358, 2021). "In fact, IL-6-knockout mice show impaired innate and adaptive immunity to infection by parasites, bacteria, and viruses." (PMID 33786327, 2021). "In the later phase of the infection, starting from day 6 or 9, the mRNA transcription levels of perforin and granzyme B were increased in both groups, and IL-6 mRNA transcription levels were increased predominantly in the vaccinated cats." (PMID 34578316, 2021). "Mentioned, IL-6 is a pleiotropic cytokine produced in response to infection and tissue damage, produced by macrophages, T and B lymphocytes, and non-immune cells." (PMID 34943009, 2021). "IL-6 activates lymphocytes, leukocytes, and eosinophils infiltration to the site of infection and upregulation of SOCS-1 and SOCS-3 expression in IBV-infected cells serve as the feedback system of IL6 signal transduction." (PMID 33406695, 2021). "It has been reported that the infection with SARS-CoV-2 can cause a cytokine storm in patients with symptoms severe or critical, consisting of an increase of IL-1β, IL-4, IL-6, IL-10, IL-17, TNF-α, G-CSF, GM-CSF, IFN-γ, CCL2, CXCL8, and CXCL10." (PMID 33917837, 2021). "The ideal therapy should correct the dysfunction of the innate immune response to SARS-CoV-2 which leads to excess inflammation and over-expression of IL-6, as well as enhancing adaptive immune responses to resolve the infection and prevent re-infection." (PMID 34769119, 2021). "Rapid generation of IL-6 contributes to the host defense during tissue injury and infection, while excessive synthesis and massive accumulation of IL-6 often lead to disease pathology." (PMID 34595243, 2021). "Infection of human monocytes with K. kingae performed at MOIs of 1 and 10 elicited the secretion of IL-6, TNF-α, and IL-1β at 24 h post-infection in an inoculum-dependent manner." (PMID 34925328, 2021). "At 12 h post-infection, total cellular RNAs were extracted and the viral RNA accumulation as well as the mRNA levels of 5 inflammatory cytokines, such as IL-6, IL-1β, TNF-α, TGF-β and IL-10, were examined using qRT-PCR." (PMID 34335977, 2021).
infection (continued). "The IL-6 mRNA expression in the lungs of group IV was lower (p < 0.05) compared with levels in group I at day 1 post-infection." (PMID 34988139, 2021). "IL-6 is a pleiotropic cytokine that is known to induce release of CRP in response to inflammation or infection." (PMID 34630395, 2021). "While some expression patterns remained elevated during infection, by day 5 there was increased Il-12a, Il-12b, Il-6, Cd80, and Cxcl11 expression that corresponded with elevated Il-15 levels in young adult H1N1 and H3N2 infected lung." (PMID 34829979, 2021). "Reports of patients with encephalopathies due to local infection with Influenza virus in the brain have shown an increased transcription for IL-6, IL-10, and TNF-α in immune cells from the peripheral blood." (PMID 34916908, 2021). "IL-6 is a potent inducer of Th17 polarization and has been found elevated during murine infection with B. pertussis (45, 48, –, 50)." (PMID 34125597, 2021). "Then clinical validation results showed that IL‐12p70, G‐CSF, and IL‐6 had significant differences in the infection and non‐infection population." (PMID 34725873, 2021). "Another previous study showed that the consequences of early life stress-induced infection altered cytokine production, such as IL-6, TNF-α, or IL-1β, and changed behaviors in later life." (PMID 33441182, 2021). "There were some cytokine transcripts differentially expressed early in infection (IL6, CXCL10, and CCL3 for example), but overall only a minority of DEGs are cytokines (n = 13)." (PMID 34615921, 2021). "IL-6 secreted by monocytes and macrophages is an inflammatory mediator involved in the immune regulation of infection and tumors." (PMID 33967748, 2021). "Further RT-PCR analyses determined that the levels of IFNB1, IFIT2, IFIT1, TNF and the proinflammatory cytokines CCL20 and IL6 were enhanced by RTN3 knockdown during VSV infection, while the amplification of VSV was compromised." (PMID 34313226, 2021). "Patients who died of this fatal infection were found to have extremely high pro-inflammatory markers (interleukin-6 (IL-6)) in their first clinical case reports." (PMID 35004038, 2021). "Activation of NFκB in HIBCPP cells and NFκB-induced expression of inflammatory reaction genes, including il6, after infection with Nm has already been shown." (PMID 34863201, 2021). "IL-6 levels were higher in the ECCs of patients with multiple infections (p = 0.0380) than those patients with a simple infection, although the levels were lower than those detected in patients negative for HPV DNA." (PMID 33750983, 2021). "Infection generates high persistent PR signals that license APC to make more IL-6 in subsequent interactions with T cells, and thus can restore some of the lost response." (PMID 35382063, 2021). "Inoculation of S. suis induced IL-6 expression in WT and Fpr2−/− BMDMs, and IL-6 levels were significantly higher in Fpr2−/− BMDM supernatant after 8 or 12 h of infection." (PMID 33318141, 2021). "While homeostatic values of IL-6 contribute to the resolution of infections and tissue lesions, its exacerbated production contributes decisively to cytokine storms." (PMID 33679753, 2021). "The IL‐6 elevation after the infection is an inflammatory reaction to control neutrophil and monocyte transition during the inflammatory process." (PMID 33590677, 2021). "When infections or tissue injuries occur, IL-6 is promptly produced by monocytes and macrophages and contributes to the removal of infectious agents and restoration of damaged tissues through activation of immune, hematological, and acute-phase responses." (PMID 33628091, 2021). "A significant positive correlation between pro-inflammatory IL-6 level and the occurrence of post-traumatic infection from day 1 to 7 (day 3: r = 0.384; p = 0.007) was shown." (PMID 34568354, 2021). "Our results showed that infection of the HT-29 cells with C. jejuni induced different signaling pathways including TLRs, PPRs, IL-6, and NF-kB." (PMID 33382951, 2021).
infection (continued). "Biomarkers procalcitonin (PCT) and interleukin-6 (IL-6) have been widely used in the diagnosis and identification of infections." (PMID 33902476, 2021). "IL-6 is a target for therapy with tocilizumab, a monoclonal antibody that has demonstrated efficacy in severe infections and is under trial for approval against Sars-CoV-2." (PMID 33946649, 2021). "TNF-α and IL-1β are acute-response cytokines appearing early after infection, followed by a more sustained increase in IL-6." (PMID 33995033, 2021). "polymorphum and S. gordonii secreted significantly lower levels of IL-1β and IL-6 at 24 h post infection compared with those infected with the co-culture of both species." (PMID 35071038, 2021). "Data supporting this concept is continuously emerging and our work makes a relevant contribution by proposing that IL-6 acts as an initiator of resolution, triggered during the inflammatory phase of infection." (PMID 33504816, 2021). "Interleukin-6 (IL-6) plays a crucial role in host defense against infection and tissue injuries and is a bioindicator of multiple distinct types of cytokine storms." (PMID 34253862, 2021). "Herein, IL-6 expression was very similar for animals E1 and E2, since it was highly expressed especially in the sub-patent phase of infection." (PMID 34827923, 2021). "The pro-inflammatory molecules commonly increased during the infection with influenza virus are the IL-6, TNF-α, and IL-1β." (PMID 33917837, 2021). "Macrophages play an important role in the secretion of inflammatory cytokines such as TNF-α and IL-6, host defense against infection, and recovery of damaged tissues." (PMID 33407886, 2021). "Elevated serum C-reactive protein, a protein whose expression is driven by IL-6, is also a biomarker of severe infection." (PMID 33917093, 2021). "EcoHIV-infection induced a prominent change in various neuroinflammatory markers (i.e., IL-1β, IL-6, TNF-α, and NF-κB) in the brain relative to the control animals." (PMID 34067600, 2021). "The observed infection augmented the cytokine level and also the viral load, as well as IL-1β and IL-6 in supernatant liquids and also in viral RNA within cells." (PMID 33937285, 2021). "Deregulated and continual synthesis of IL-6 plays a pathological role in chronic inflammation and infection." (PMID 33643932, 2021). "IL-6 contributes to host defense by stimulating acute phase responses or immune reactions in response to infections and tissue injury." (PMID 33643932, 2021). "Infection with hepatitis C virus can lead to a systemic increase in the production of a variety of inflammatory cytokines, especially interleukin-6 (IL6) and tumor necrosis factor-a (TNF-α)." (PMID 34215260, 2021). "Serum IL-6 levels at 10 days post-infection showed a difference between untreated WT and KO mice (P = 0.0128), but not between ARU-treated WT and KO mice." (PMID 33731716, 2021). "IL-6 expression is tightly regulated, with low levels of expression in healthy individuals and elevated expression during infection, trauma or other stress." (PMID 34504432, 2021). "The obtained data signify the anti-inflammatory role of IL6 in establishing SOCS1/SOCS3 immune axis during the early stage of infection." (PMID 35011356, 2021). "Pa infection induced IL-6 in a time-dependent manner increasing from 2 to 24 hours post infection with a peak 97.4-fold induction (IQR, 62.0–125.0)." (PMID 33524056, 2021). "Intriguingly, A5+ treatment strongly reduced IL-6 cytokine production in influenza virus-infected cells, suggesting its potential anti-inflammatory properties during the infection." (PMID 34829949, 2021). "Expression of IL-6 and amyloid A were strongly positive in 7 baboon livers (Rejection group, n=6, and Infection group, n=1)." (PMID 34956220, 2021). "Taken together, in priming inflammatory responses and activating adaptive immunity against infection or injury IL-6 is a key cytokine." (PMID 34803441, 2021).
infection (continued). "In an experiment with HRV14, another HRV strain used ICAM-1 as receptor for entrance of epithelial cells, IL-6 and IL-8 levels were found to increase by the infection." (PMID 34001091, 2021). "In conclusion, these data indicate that infection of human innate immune cells with SARS-CoV-2 mediates only a slight increase in the release of pro-inflammatory IL-6 induced by secondary infections or stimulation." (PMID 34122407, 2021). "The expression levels of TNF-α, IL-6, IL-8, and IL-10 at different infection time points were higher than those in the control group, especially at 36 hpi." (PMID 33597007, 2021). "The presence of IL-6 is due to the pathophysiological profile of CLA, which leads to a greater production of IL-6 which is responsible for attracting macrophages and neutrophils to the site of infection." (PMID 34843474, 2021). "IL-6 is involved in enhancing the early pro-inflammatory response to TB as well as promoting T-cell and B-cell induction in the later infection stages." (PMID 33805837, 2021). "KO of MyD88 showed an even greater reduction in both IL-6 and TNFα secretion from 3 to 48 h post infection." (PMID 34280250, 2021). "Infection with SARS-CoV-2 causes elevated production of pro-inflammatory cytokines such as tumor necrosis factor α (TNF-α), interleukin 6 (IL-6), and interleukin 12 (IL-12) which potentiate the innate immune response." (PMID 34690821, 2021). "Here, we corroborate these findings in Calu-3 cells using an unbiased genome-wide methodology showing that antiviral cytokines (IFNL1-3, IFNB1, CCL5, CXCL11 and IL6) are restricted in translation at 24 h post infection." (PMID 33806254, 2021). "Nevertheless, the RNA levels of IL-6, CCL2 and CXCL10 decreased after 5 days of infection, especially IL-6 that went down with more than 5-fold reduction compared to that on day 2 post infection." (PMID 34379705, 2021). "IL-6 regulates multiple functions in the liver, including infection defence, metabolism, and regeneration." (PMID 34047814, 2021). "Taken together, the sites of infection showed a clear increase in inflammatory markers, especially IL-6 in the nasal turbinates and TNF in the lung." (PMID 34265022, 2021). "Interleukin 6 (IL-6) is produced quickly and transiently during tissue infection and injury and promotes host defense by stimulating acute phase response, hematopoiesis, and immune response." (PMID 34335867, 2021). "Serum IL-6 was also elevated to a significant or near significant level in Dectin-2 KO mice following infection with C. albicans and C. tropicalis similar to our previous observations." (PMID 33717025, 2021). "Their research, as well as ours, have revealed the benefits of cytokines IL-6, IL-8, and IL-10 in accurately predicting infections with a short detection time and high sensitivity." (PMID 34925324, 2021). "To investigate if TNF-α and IL-6 signaling contributes to controlling the infection, we treated infected macrophages with infliximab or tocilizumab and measured the fluorescence intensity of M. avium-DsRed to assess the burden per infected cell." (PMID 34607464, 2021). "ELISA confirmed that the increased cytokine production (CXCL1, CXCL2, IL-6, and IL-1β) induced by bacterial infection was reverted by AnxA1 treatment in WT mice at 14 h after infection." (PMID 33318141, 2021). "Since Ferritin and IL-6 are acute-phase proteins, their higher contents indicate a more severe inflammatory response to fight infection." (PMID 34356769, 2021). "The levels of pro-inflammatory cytokines (TNF-α, IL-1β, IL-6, and IL-8) were markedly higher after infection than those in the normal control group." (PMID 33670217, 2021). "From all these data, an overall model emerges where upon infection, let-7 and RanBP2 modulate the inflammatory response by downregulating IL6, and potentially other cytokines." (PMID 33600493, 2021).